SMAD4 (SMAD family member 4)
Diseases named in the same sentence as SMAD4 in open-access papers (continued):
Sharing a sentence is not in itself a finding about the gene and the disease.
infection (29 papers, 2011 to 2025). The state of being infected such as from the introduction of a foreign agent such as serum, vaccine, antigenic substance or organism. "ATF4 and SMAD4 each associated with suppression of target genes in the WT BMM response to WNV while suppression is lost in the DKO BMM response to infection (compare left and right panels, respectively)." (PMID 31409781, 2019). "In line with this, the frequency and the number of Smad4-deficient Kb-ova+CD8+ splenic T cells were similar to those of control cells 5 days after the secondary infection." (PMID 26583325, 2015). "Consistently, Smad4 deficiency led to partially diminished GzmB expression in Kb-ova+CD8+ splenic T cells upon OVA peptide restimulation 5 days after the secondary infection." (PMID 26583325, 2015). "In order to address the biological role of SMAD4 inactivation in HNSCC we sought to rescue SMAD4 function by infection with an inducible lentivirus encoding a Flag-tagged wild type version of SMAD4." (PMID 25275298, 2014). "Finally, Alk1/Smad4-deficient mice showed an increased susceptibility to infection with gram-positive L. monocytogenes." (PMID 34874921, 2022). "Since very few SMAD4-deficient CTLs expressed KLRG1 during infection with LM-OVA, we investigated whether these cells were located in the vasculature or peripheral tissues." (PMID 35942952, 2022). "Next, whether Smad4 deficiency impacts on effector functions was explored 7 days after LM-OVA primary infection." (PMID 26583325, 2015). "To make it clear whether the Smad4-deficient CD8+ T cells maintain or re-express CD127 at high level at day 7 post infection of LM-OVA, we checked CD127 expression at earlier time points." (PMID 26583325, 2015). "Thus, Smad4-deficient CD8+ T cells maintain high CD127 expression after LM-OVA infection." (PMID 26583325, 2015). "Two of the main SMAD pathway elements, SMAD2 and SMAD4 are less robustly regulated during infection, with SMAD2 showing minor upregulation at L timepoints." (PMID 39863683, 2025). "Confocal microscopy analysis demonstrated that cMyc and SMAD4 shuttle to the nucleus during infection, and nuclear localization is reduced when ERK is inhibited." (PMID 31561471, 2019). "It has been shown that SUMOylation of SMAD4 is necessary to respond to TGF-β which is involved in host resistance against infection with L. monocytogenes." (PMID 30634511, 2019). "SMAD4, down-regulated during infection, binds receptor-regulated SMADs to serve as a transcription activator that regulates TGF-beta receptor-mediated signaling." (PMID 25903558, 2015). "This approach ensures that Smad4-deficient and Smad4-sufficient CD8+ T cells are exposed to identical concentrations of antigen and inflammation during infection." (PMID 26583325, 2015). "To understand the effect of Smad4 loss on memory, we analyzed the proportion of OVA antigen-specific memory CD8+ T cells in Smad4-sufficient and -deficient CD8+ splenic T cells 35 days after primary infection." (PMID 26583325, 2015). "Meanwhile, the results also revealed that the expression of α-SMA and Smad4 were up-regulated significantly in the fibrotic livers at 8 weeks post-infection, compared with the normal livers." (PMID 24685242, 2014). "We also found that the expression of phosphorylation of SMAD1/5/8 and SMAD4 were increased by 2.4 and 2.1 fold respectively at 8 hr of infection than at 4 hr and untreated which is generally accepted as readout of an active BMP pathway by Western blot." (PMID 25365201, 2014). "Alpha-smooth muscle actin (α-SMA), collagen I, collagen III, TGF-β1, Smad2, Smad3, and Smad4 showed a significant increase in mitochondrial RNA (mRNA) and protein expression compared with the control group at 7 and 9 weeks post-infection (wpi), while an opposite effect on Smad7 was observed." (PMID 36474240, 2022). "Interestingly, the expression of Smad7 dramatically decreased after 7 wpi, whereas Smad4 continued to increase after infection." (PMID 36474240, 2022).
infection (continued). "Interestingly, several transcription factors were upregulated in comparison to mock-infected samples at 24 hpi including cMyc, Elk-1, SMAD4, and cJun, suggesting that JCPyV positively upregulates MAPK-ERK-associated transcription factors during infection." (PMID 31561471, 2019). "However, the mRNA expression of SMAD4 was up-regulated at 36 h and 48 h post-infection, which again suggested that SENP1 regulated the protein expression at post-translation level, in consistent with the results in PC3M cells." (PMID 28417919, 2017). "Smad4 overexpression was conducted by infection of a Smad4-overexpressing lentivirus." (PMID 29167750, 2017). "Researchers have identified increases in the expression of several genes (SMAD3, SMAD4, COL1A1) related to TGF-β and associated with evidence of fibrosis-associated cell types, including fibroblast and stellate cell lines, in acute stages of infection in sheep." (PMID 29970179, 2018). "Moreover, SENP1 over-expression reduced SMAD4 protein expression at 48 h after infection." (PMID 28417919, 2017). "Thus, Smad4 contributes to the cytotoxic function of CD8+ T cells in primary infection." (PMID 26583325, 2015). "Two days pre-intravitreal injection, Myh11-derived MSCs (derived from Myh11-tdTomato mice) were infected at 3000 MOI of Smad4-shRNA or scramble-shRNA adenovirus vectors, with co-expression of GFP indicating successful infection." (PMID 32978500, 2020). "Previous studies have identified numerous host-cell transcription factors usurped by JCPyV during infection including cMyc, AP-1 (cJun and cFos), NFAT4, SMAD4, YB-1, NF-1, and others." (PMID 31561471, 2019). "However, Smad4 deficiency did not affect the proliferation up to 14 days post infection." (PMID 26583325, 2015). "None of the immune mice experienced substantial weight loss after infection with WSN-OVAI, indicating that protection against reinfection was not dependent on SMAD4 or TGFβ." (PMID 35942952, 2022). "We found promising master regulators of duck genes in lung and ileum (RUNX2, SMAD3, SMAD4, and ETS1), which could be responsible for the duck’s effective differential gene expression in response to HPAI infection." (PMID 35205087, 2022). "Because of the essential effects of Smad4 in the control proper CD4+ T-cell differentiation, consequently changes in CD4+ T cell help or Treg function could alter the course of infection." (PMID 26583325, 2015). "We found that those CRISPR-targeted cells with decreased ACE2 expression (SMAD4, EP300, and PIAS1) also exhibited a decrease in both the proportion of infected cells by SARS-CoV-2 nucleocapsid protein immunofluorescence and in viral infectivity by TCID50 at 48 hours post-infection." (PMID 35231079, 2022). "Lower transcription levels of NUDT14, KLK10, SLC28A1, SMAD4 and SEPT7 during a series of stages of infection may reflect the inabilities of these genes to participate in glucose metabolism, tumorigenesis, nucleoside biosynthesis and transport, signaling and microtubule stabilization respectively." (PMID 25903558, 2015). "To explore whether Smad4 also controls the generation of cytotoxic effector cells from memory CD8+ T cells, we challenged Smad4co/co;Lck-Cre mice and their littermates with a higher dose of LM-OVA 35 days after primary infection." (PMID 26583325, 2015). "Primary astrocytes may induce an immune response by releasing cytokines and chemokines early during infection, not seen in SVGAs, but in turn, the virus slowly activates transcription factors, like Smad4 from the TGF-β signaling pathway to support viral replication in the nucleus of NHAs." (PMID 34578413, 2021).
connective tissue disorder (8 papers, 2015 to 2026). A disease involving the connective tissue. "We also find evidence for activation of multiple other inflammatory and connective tissue-disorder pathways mediated through pro-inflammatory TF genes such as STAT3, IRF1 and IRF7, CEBPB and SMAD4." (PMID 26202100, 2015).
gastrointestinal tumors (8 papers, 2008 to 2025). "Loss of SMAD4 activity is a common characteristic of gastrointestinal tumors and is most frequently observed in CCA originating in the distal common bile duct, near the pancreas—where SMAD4 mutations are particularly prevalent." (PMID 39199659, 2024). "Mutations in SMAD4 lead to the formation of gastrointestinal tumours." (PMID 37962020, 2023). "Notably, loss of a single Smad4 allele in T-cells also resulted in hyperplasia and polyp formation in the intestinal epithelial layer, thus indicating that Smad4 haploinsufficiency plays a causative role in GI tumor formation by exerting a 'landscaping' effect from within the stromal compartment." (PMID 19014666, 2008).
genetic disease (8 papers, 2020 to 2025). "It is a genetic disorder with an autosomal dominant form of inheritance, and pathological variants in the SMAD4 gene (17%–35%) or the BMPR1A gene (17%–25%) have been established as the cause." (PMID 38191939, 2024). "We suggest that further studies could explore losartan (or other therapies acting on the SMAD4 pathway) as a potential targeted therapeutic option for cutaneous fibrosis associated with this rare genetic disease." (PMID 32917212, 2020).
colon polyps (7 papers, 2022 to 2024). "The two brothers inherited the SMAD4 c.425-9A>G variant from their mother, who also harbored an APC pathogenic variant and developed CRC and numerous colon polyps with different histological classifications (hamartomatous, juvenile, and adenomatous)." (PMID 39063183, 2024). "Mutations in MADH4/SMAD4 cause juvenile polyposis/HHT overlap syndrome (JPHT), which generates, additionally to HHT symptoms, colon polyps and thoracic aneurysms." (PMID 38892351, 2024). "Both patients in whom we detected a PV in SMAD4 had 10–20 colonic polyps removed over a period of 15–20 years, that had shown inflammatory or hyperplastic histopathology with only few polyps suspected to be juvenile." (PMID 37354305, 2023).
colorectal (7 papers, 2005 to 2023). "Loss of tumor suppressor SMAD4, its decreased level, and posttranscriptional regulation are all known mechanisms involved in colorectal carcinogenesis." (PMID 35034624, 2022). "SMAD4 has also been suggested to be genetically responsible for familial juvenile polyposis and also has been implicated as a late genetic event in colorectal carcinogenesis." (PMID 17587453, 2007).
cardiovascular disease (3 papers, 2018 to 2023). "Analysis of the interactome and disease-related network on the 44-dysregulated genes identified HDAC9, SMAD4, PTGFR, and PRKCE as the highest scoring genes within the cardiovascular disease category." (PMID 29520069, 2018).
gastrointestinal disease (2 papers, 2007 to 2023). A disease that occurs in the gastrointestinal system, excluding the hepatobiliary system. "Collectively, these results highlight an integral role of the TGF‐β/Smad4 axis in restraining intestinal inflammation and tumorigenesis and suggest TGF‐β or YAP signaling as therapeutic targets for these gastrointestinal diseases intervention." (PMID 37261975, 2023).
head and neck tumor (2 papers, 2013 to 2021). "Inflammatory mediated genetic alterations were previously observed in the head and neck tumor mice model, in which SMAD4−/− deletion in head and neck epithelia resulted in genetic aberrations and deletion of chromosome 4q in SMAD−/− mice." (PMID 23408900, 2013).
neurodevelopmental disorder (2 papers, 2021 to 2022). A behavioral and cognitive disorder with onset during the developmental period that involves impaired or aberrant development of intellectual, motor, or social functions. "Considering the miRNA and piRNA target genes common to multiple samples, four were already present in SFARI database: NACC1, SMAD4, TNRC6B, and TTN, and their mutants are implicated in ASD and other neurodevelopmental disorders." (PMID 35405953, 2022).
vascular disorder (2 papers, 2013 to 2021). A general term used to describe any disease affecting blood vessels]. "HHT is a vascular disorder and the research of the last 20 years has shown that the TGF-ß/BMP receptors endoglin and ALK1 and Smad4, as an intracellular signal transducer protein, are involved in the different angiogenic processes." (PMID 23805858, 2013).
benign tumour (1 paper, 2013).
gastroenteropathy (1 paper, 2024). "Therefore, TG and PD were performed for JPS caused by the SMAD4 mutation, which presented with anemia and protein-leakage gastroenteropathy that were difficult to treat medically." (PMID 38191939, 2024).
skeletal dysplasia (1 paper, 2017). Any Mendelian diseases that affects growth and development of the skeleton. "Several aspects of the aggrecan-deficient growth plate resemble those observed in Smad4-deficient growth plates, including skeletal dysplasia, loss of aggrecan expression, reduced chondrocyte proliferation, and deregulation of chondrocyte shape and organization." (PMID 28167493, 2017).
SMAD4 also shares sentences with these, for which no sentence is quoted: Lynch syndrome (8 papers); Peutz-Jeghers syndrome (7); gastric polyposis (5); hereditary mixed polyposis syndrome (4); sarcoma (4); adenosquamous carcinoma (3); Alzheimer disease (3); Cowden syndrome (3); epistaxis (3); idiopathic pulmonary fibrosis (3); metastatic prostate carcinoma (3); Pancreatic cysts (3); pulmonary hypertension (3); type 2 diabetes mellitus (3); allergic disease (2); Arthritis (2); colon (2); Dyslipidemia (2); endocrine pancreatic carcinomas (2); goblet cell adenocarcinomas (2); hepatitis viral ( (2); hereditary cancer syndrome (2); infectious disease (2); Insulin resistance (2); intestinal type adenocarcinoma (2); intraepithelial neoplasia (2); kidney disease (2); large cell neuroendocrine carcinoma (2); leukoplakia (2); mutyh-associated polyposis (2).
A further 141 diseases each share a sentence with SMAD4 in 2 papers or fewer.